HOXA5 (homeobox A5)
Diseases named in the same sentence as HOXA5 in open-access papers (continued):
Sharing a sentence is not in itself a finding about the gene and the disease.
breast carcinoma (continued). "HOXA5 down-regulation is discovered in multiple tumors, including liposarcoma, cervical cancer, breast cancer, which suggests that HOXA5 may be an important tumor suppressor." (PMID 34722321, 2021). "Taken together, these observations demonstrate that HOXA5 is overexpressed at least in some subset of breast cancer and may contribute to breast cancer growth." (PMID 33384715, 2020). "Interestingly, these analyses show that HOXA5 expression is elevated in most breast cancer tissues relative to their normal counterparts." (PMID 33384715, 2020). "The enrichment of histone acetyl-transferases (CBP/p300) and histone H3K4 trimethylases (MLL2 and MLL3) and the histone acetylation and H3K4 trimethylations at the HOXA5 promoter in the presence of E2 suggest their important roles in E2-mediated regulation of HOXA5 expression in breast cancer." (PMID 33384715, 2020). "HOXA5 expression is critical for breast cancer cell viability." (PMID 33384715, 2020). "Additionally, c-bioportal-based meta-analysis of preexisting gene expression databases in breast cancer patients also show that HOXA5 expression is elevated in breast cancer patients." (PMID 33384715, 2020). "Additionally, our studies also demonstrate that HOXA5 expression is important for cell-cycle progression as well as cell viability of breast cancer cells." (PMID 33384715, 2020). "HOXA5 downregulation results in cell-cycle arrest and apoptosis in breast cancer cells." (PMID 33384715, 2020). "In addition, retinoid acid (RA) bound to retinoid acid receptors (RARs) and transcriptionally activated Hoxa5, which was important for RA-mediated apoptosis increase and proliferation inhibition in a variety of breast cancer cells." (PMID 29221131, 2017). "HOXA5 has been suggested to be a potential tumor suppressor in breast cancer." (PMID 27755609, 2016). "HOXA5 was also shown to interact with the transcription factor TWIST in breast cancer cell lines." (PMID 29615582, 2016). "Recent studies indicate that homeobox A5 (HOXA5) may serve as a tumour suppressor gene in breast cancers." (PMID 25875824, 2015). "These analyses demonstrate that HOXA5 expression is significantly amplified in various breast cancer tissues, such as in MBC project, BRCA, breast (METABRIC), and invasive breast carcinoma (TCGA PanCan), further suggesting potential association of HOXA5 in breast cancer." (PMID 33384715, 2020).
breast carcinoma (continued). "Nevertheless, our studies demonstrate that HOXA5 expression is upregulated, at least in a subset of breast cancer, and is regulated by estrogen in vitro and in vivo, and therefore, may play critical roles in in breast cancer." (PMID 33384715, 2020). "Furthermore, Up-regulation of HOTAIR and methylation of HOXA5 were found during the development of breast cancer and a previous study indicated that HOTAIR and homeobox A5 (HOXA5) worked together and were closely correlated to growth and metastasis of non-small cell lung cancer." (PMID 31168296, 2019). "Similarly, HOXA5 is also regulated by miR-130 in human breast cancer cells." (PMID 26219418, 2015). "The WNT signaling pathway appears to regulate HOXA5 expression through modulation of the MYC-MIZ1 complex, suggesting complex crosstalk between these pathways in breast cancer pathogenesis." (PMID 40758729, 2025). "It favours the proliferation of breast cancer cells by repressing tumour suppressor genes such as BRCA1 and HOXA5." (PMID 37187521, 2023). "AKR1B1, RASGRF2, CRMP1, BNIP3, GSTP1, HOXA5 and PAX6 genes were methylated in ER-positive and HER2-negative breast cancer with ALNM." (PMID 36454866, 2022). "In line with this, several potential tumor-suppressive genes including HOXA5 and ELF3 have been shown to be upregulated by retinoids in breast cancer cells." (PMID 36497371, 2022). "HOXD10, HOXA5, and SEC61G have all been shown to play an important role in breast tumorigenesis and were identified as potential biomarkers for the diagnosis of breast cancer." (PMID 36531217, 2022). "CAF‐derived exosomes were able to enhance breast cancer cell proliferation and to induce the epithelial‐mesenchymal transition via the regulation of the CDX2/HOXA5 pathway." (PMID 35857905, 2022). "Therefore, based on all our observations, we propose that overexpression of HOXA5 in breast cancer may not cause the cancer cell to revert back to a normal-like state." (PMID 34149926, 2021). "Recently, Wang and coworkers reported that CAF-derived exosomes carrying miR-181d-5p function as promoters in the EMT, invasion and migration of MCF-7 breast cancer cells, reducing the expression of Caudal-related homeobox 2 (CDX2) and homeobox A5 (HOXA5)." (PMID 32764376, 2020). "We transfected HOXA5 cDNA in lung cancer cell lines (LHK2, A549 and Sq-1 cells) and breast cancer cell lines (MCF7 cells)." (PMID 27418136, 2016). "Exosomes released from cancer-associated fibroblasts (CAFs) loaded with miR-181d-5p could be taken up by breast cancer cells and impair apoptosis via downregulating CDX2 and HOXA5." (PMID 36338993, 2022).
breast carcinoma (continued). "Therefore, our study identified RHOF, CRMP1, BNIP3 and HOXA5 as novel candidate methylation biomarkers, which can be used to predict ALNM in breast cancer or ER-positive and HER2-negative breast cancer." (PMID 36454866, 2022). "Furthermore, in addition to highly methylated AKR1B1, RASGRF2 and CRMP1 gene promoters, BNIP3, GSTP1, HOXA5 and PAX6 gene promoters were also methylated in ER-positive and HER2-negative breast cancer with ALNM." (PMID 36454866, 2022). "Moreover, in addition to highly methylated AKR1B1, RASGRF2 and CRMP1 gene promoters, BNIP3, GSTP1, HOXA5 and PAX6 gene promoters were also methylated in ER-positive and HER2-negative breast cancer with ALNM." (PMID 36454866, 2022). "Targeted bisulfite sequencing showed that the promoter methylation levels of AKR1B1, BNIP3, CRMP1, GSTP1, HOXA5, PAX6, and RASGRF2 were increased in ER-positive and HER2-negative breast cancers with ALNM, compared with ER-positive and HER2-negative breast cancers without ALNM." (PMID 36454866, 2022). "In contrast, HOXA5 expression is absent in several breast cancer cell lines and mammary carcinomas, and its absence correlated with higher pathological grades." (PMID 31159758, 2019). "Given the established inhibitory effects of artesunate on breast cancer, we hypothesize that its anticancer activity may be mediated through down-regulation of lncRNA TUG1, subsequent activation of miR-145-5p, and inhibition of the HOXA5/WNT signaling axis." (PMID 40758729, 2025). "Besides, in breast cancer, CAFs exosomal miR-181d-5p facilitated EMT by regulating CDX2/HOXA5." (PMID 36319622, 2022). "In the current study, we suggest that targeting the overexpression of HOXA5 alone in breast cancer cells may not be therapeutically beneficial to combat tumorigenesis." (PMID 34149926, 2021). "In breast cancer, CAFs-derived exosomes carrying miR-181d-5p can promote proliferation, invasion, migration, and EMT and inhibit apoptosis of cancer cells by targeting caudal-related homeobox 2 (CDX2) and then downregulating CDX2 and its downstream gene -homeobox A5 (HOXA5)." (PMID 34852849, 2021). "Furthermore, in addition to highly methylated AKR1B1, RASGRF2 and CRMP1 gene promoters, BNIP3, GSTP1, HOXA5 and PAX6 gene promoters were also methylated in ER-positive and HER2-negative breast cancer with ALNM, which may serve as candidate methylation biomarkers." (PMID 36454866, 2022). "More importantly, survival curves from ER+ breast cancer patients without tamoxifen treatment were independent of HOXA5 expression as compared to survival curves of patients who received tamoxifen treatment, which demonstrated that a higher expression of HOXA5 resulted in a poorer overall survival." (PMID 34149926, 2021). "Although Hoxa5−/− mice do not develop mammary tumors, the epithelial mispecification and the hyperplasia seen in the mammary glands of Hoxa5−/− females suggest a protective role for Hoxa5 toward cancer predisposition and reinforce the notion that Hoxa5 may possess tumor-suppressive properties." (PMID 29615582, 2016). "And compared with ER-positive and HER2-negative breast cancers without ALNM, the methylation levels of AKR1B1, RASGRF2, CRMP1, BNIP3, GSTP1, HOXA5, and PAX6 promoter were increased in ER-positive and HER2-negative breast cancers with ALNM." (PMID 36454866, 2022).
lung cancer (31 papers, 2009 to 2025). A malignant neoplasm involving the lung. "Loss of HOXA5 expression has been associated with increased methylation of its promoter in human breast and lung cancers." (PMID 35203377, 2022). "Nevertheless, the specific role and the underlying mechanisms of HOXA5 in lung cancer remain unknown." (PMID 25875824, 2015). "To investigate whether the effect of HOXA5 on lung cancer invasion and migration is associated with actin filament dynamics, we examined the cellular location and distribution of actin filaments with confocal microscopy." (PMID 25875824, 2015). "HOXA2, HOXA3, and HOXA5 have been recognized as target for DNA methylation in lung cancer, and they promoted carcinogenesis, but also acted as tumor-suppressor factors." (PMID 34262872, 2021). "HOXA5 has been reported to be deregulated in several malignant tumors, including colorectal cancer, lung cancer, cervical cancer, and gastric cancer 31-35." (PMID 32373208, 2020). "Another study shows that oxidative stress–mediated repression of HDAC8 induces histone H3 acetylation and HOXA5 expression that controls plasticity of lung cancer stem-like cells." (PMID 33384715, 2020). "A549 lung cancer cells also showed high expression of HOXA5 short RNA when compared with normal lung epithelial cells (BEAS-2B)." (PMID 31159758, 2019). "To exhibit the clinical significance of HOXA5, we initially searched two microarray data sets from Garber and Bhattacharjee lung cancer cohorts on Oncomine website." (PMID 28423732, 2017). "Previous studies showed that the promoter region of HOXA5 is inactivated by DNA methylation in breast and lung cancer cells." (PMID 27418136, 2016). "Several studies have investigated HOXA5 gene expression in human lung cancers; however, the results of these studies are contradictory." (PMID 25875824, 2015). "However, the precise role and the underlying mechanism of HOXA5 in lung cancer remain unclear." (PMID 25875824, 2015). "We then examined the expression of HOXA5 in other lung cancer cell lines, including A549, H322M, and PE089." (PMID 25875824, 2015). "To date, there have been few studies of HOXA5 gene expression in human lung cancer, but their results are contradictory." (PMID 25875824, 2015). "Among the HOTAIR-regulated genes in lung cancer cells, HOXA5 is of particular interest because of its established roles in lung development and tumorigenesis." (PMID 25491133, 2014). "A possible tumour-suppressor role for HOXA5 is also supported by low HOXA5 expression in breast and lung cancer tissues which is thought to be mediated by methylation of the CpG island located on the 5' end of the HOXA5 gene." (PMID 21906307, 2011). "Furthermore, HOXA5 acts as a tumor suppressor to inhibit the angiogenesis of hepatocellular carcinoma and induces the apoptosis of lung cancer cells." (PMID 36167790, 2022). "Finally, ectopic over expression of HOXA5, a master regulator of morphogenesis and cell differentiation that is commonly downregulated in lung cancers, inhibited cell proliferation and invasion." (PMID 33632299, 2021). "HOXA5 also affects tumor cell proliferation and invasion in cervical cancer and lung cancer." (PMID 34485110, 2021). "HOTAIR was demonstrated to downregulate HOXA5 in lung cancer." (PMID 31168296, 2019).
lung cancer (continued). "Protein expression of HOXA5 was detected in TSA-treated lung cancer cells." (PMID 27418136, 2016). "Knockdown of HOXA5 promoted the invasiveness of lung cancer cells." (PMID 25875824, 2015). "Whether HOXA5 regulates various lung cancer-related genes or what changes it undergoes in lung adenocarcinoma, remains to be elucidated." (PMID 26035298, 2015). "The expression of HOXA5 was low in these tested lung cancer cell lines, except for CL1-0 cells." (PMID 25875824, 2015). "Our studies provide new insights into how HOXA5 may contribute to the suppression of metastasis in lung cancer via cytoskeleton remodelling regulation." (PMID 25875824, 2015). "Taken together, these results indicate that the overexpression of HOXA5 could reduce lung cancer cell invasion and migration capabilities and re-silencing of HOXA5 is able to restore the invasive capability of these cells." (PMID 25875824, 2015). "Taken together, although the precise roles of HOXA5 in lung cancer progression remain to be elucidated, we showed here that HOXA5 might act as a suppressor of metastasis during lung tumour progression, at least partly through the inhibition of calcium-mediated actin cytoskeleton polymerisation." (PMID 25875824, 2015). "Promoter methylation could be involved in tissue specific silencing of these genes and had been reported for the Hoxa5 gene in lung cancer, in human breast tumors, in myeloid and lymphoid malignancy and for the Hoxb5 gene in ovarian carcinomas where the gene undergoes de novo methylation." (PMID 19812696, 2009). "As for its upstream modulator, only HOXA5 has been reported to bind to the promoter of LINC00312 and upregulate the expression of LINC00312, leading to increased apoptosis in nonsmall cell lung cancer (NSCLC)." (PMID 32340273, 2020). "One study demonstrated that the HOXA5 gene was less methylated in non-malignant lung tissues than in paired lung cancer tissues." (PMID 25875824, 2015). "The top ranking pathways influenced by HOXA5 include cytoskeleton-related pathways such as IP3 signalling, EMT regulation, cell adhesion, and RhoA regulation, which are of particular interest due to their potential roles in lung cancer invasion and metastasis." (PMID 25875824, 2015). "In NSCLC tissues, many onco-miRs/tumor suppressor-target or tumor suppressor-miRs/onco-target pathways have been demonstrated to participate in the tumorigenesis of lung cancer, including miR7/BCL2 axis, miR-99b/FGFR3 axis, miR-101/EZH2 axis, miR-192/RB1 axis and miR-196/HOXA5 axis." (PMID 25012722, 2014). "Although other members of the HOX gene family, such as HOXA5, HOXA10, HOXB3, HOXB4, and HOXC618,19, have been found to be overexpressed in lung cancer tissues compared with normal tissues, little is known about the expression and biological function of HOXA4 in lung cancer." (PMID 29700285, 2018). "Hypermethylation and/or the downregulation of some of the genes identified in our study (e.g. ALDH1A2, HOXA5, MT1E, SOX17) have been reported in other cancers, but not yet in lung cancer." (PMID 22768131, 2012). "Interestingly, HOXA5 is also down-regulated by another HOX cluster derived non-coding RNA, miR-196a, whose expression is inversely correlated with HOXA5 in lung cancer." (PMID 25491133, 2014).